CPSF6 (cleavage and polyadenylation specific factor 6)
Diseases named in the same sentence as CPSF6 in open-access papers (continued):
Sharing a sentence is not in itself a finding about the gene and the disease.
HIV-1 infection (continued). "Overall, these results indicate that the translocation of CPSF6 to nuclear speckles is important for the recruitment of CPSF5 and LEDGF/p75 to nuclear speckles upon HIV-1 infection." (PMID 41405390, 2026). "This study suggests that HIV-1 infection–induced translocation to nuclear speckles affects the cellular functions of CPSF5 and CPSF6." (PMID 41405390, 2026). "Furthermore, given the established role of CPSF6 in HIV-1 infection, the Mtb-induced release of CPSF6 from NUDT21 in co-infected individuals could potentially exacerbate HIV-1 replication, posing a public health concern, particularly in regions with high co-prevalence of both TB and HIV." (PMID 40384984, 2025). "For example, HIV-1 infection has been reported to be marginally enhanced in CKO HEK293T cells and certain CPSF6-depleted cell lines in single-round infection assays." (PMID 40202316, 2025). "Either of these steps could be influenced by CPSF6–CA binding, since CA regulates both reverse transcription and post-reverse transcription steps (45, 46, 83, 84, 118, –, 121) and the CPSF6–CA interaction affects nuclear entry and post-entry steps of HIV-1 infection." (PMID 40202316, 2025). "In order to investigate CPSF6 function during HIV-1 infection, we first infected a range of cell types with HIV-1-GFP, immunostained for CPSF6 and the nuclear speckle marker SC35 and imaged by confocal microscopy." (PMID 38793552, 2024). "To better understand the role of CPSF6 in HIV-1 infection, we used CRISPR-Cas9 ribonucleoproteins (crRNPs) to knock-out CPSF6 in primary CD4+ T cells from four independent donors." (PMID 39678349, 2024). "Our results support these findings, as we found only the full-length CPSF6, which contains an intact IDR, formed condensates following HIV-1 infection." (PMID 38979149, 2024). "To better understand the role of CPSF6 in HIV-1 infection, we used CRISPR-Cas9 gene editing to knock-out CPSF6 in primary CD4 + T cells." (PMID 39678349, 2024). "CPSF6 condensates induced by HIV-1 infection of A549 cells (MOI of ~ 2 for 24 h) and then treated with 3% w/v 1,6-hexanediol for 3 min resulted in the disassembly of CPSF6 condensates." (PMID 37414787, 2023). "CPSF6 condensates induced by HIV-1 infection colocalized with CPSF5, indicating that these HIV-1-induced condensates contain at least two proteins, CPSF6 and CPSF5." (PMID 37414787, 2023). "These experiments indicated that HIV-1 infection induces condensates that are likely to contain the tetramer with two subunits of CPSF5 and two subunits of CPSF6." (PMID 37414787, 2023). "Similar to Nup153 and CPSF6, TRIM5 fusions to the FG-rich portion of POM121 inhibit HIV-1 infection." (PMID 37355754, 2023). "Our investigations revealed that HIV-1 infection of human T cells and macrophages induces the formation of condensates containing CPSF5 and CPSF6." (PMID 37414787, 2023). "To further characterize the condensates induced by HIV-1 infection, we used colocalization experiments to assess the presence of CPSF5 and/or CPSF7 in CPSF6 condensates." (PMID 37414787, 2023). "We found condensates containing CPSF6/CPSF5 in human T cells and human primary macrophages upon HIV-1 infection." (PMID 37414787, 2023). "Consistent with the virology experiments with full-length CPSF6 constructs, substitutions of both N- and C-terminal LCRs impaired the ability of CPSF61-358 to restrict HIV-1 infection." (PMID 36202818, 2022). "The mechanism behind this resistance to HIV-1 infection was due to a strong decrease in HIV-1 integration probably related to the defective transport of CPSF6 by TNPO3 and the formation of TNPO3-CPSF6-capsid complexes." (PMID 35646913, 2022). "While we have only discussed CypA, TRIM5α and CPSF6, numerous other cellular factors can bind to the HIV-1 capsid and have been extensively described to promote or inhibit HIV-1 infection." (PMID 34835043, 2021).
HIV-1 infection (continued). "While CPSF6 depletion has little effect on WT HIV-1 infection in these in vitro assays, infection by HIV-1T210K and HIV-1G89V was increased by CPSF6 depletion, in a cell-type specific manner." (PMID 30084827, 2018). "To understand the role of CPSF6 in the ability of TNPO3-depleted HeLa cells to inhibit HIV-1 infection, we measured HIV-1 infectivity in HeLa cells simultaneously silenced for the expression of TNPO3 and CPSF6." (PMID 23622145, 2013). "PF74 and CPSF6 accordingly each competed with NUP153C for binding to the HIV-1 CA pocket, and significantly higher concentrations of PF74 were needed to inhibit HIV-1 infection in the face of Trim-NUP153C expression or NUP153 knockdown." (PMID 24130490, 2013). "Depletion of TNPO3 expression inhibits HIV-1 infection; however, the simultaneous depletion of TNPO3 and CPSF6 expression rescues HIV-1 infectivity indicating that CPSF6 is required for the ability of TNPO3-depleted cells to block HIV-1 infection." (PMID 23622145, 2013). "We investigated whether HIV-1 infection–induced changes in CPSF5 and CPSF6 subcellular localization are accompanied by APA changes." (PMID 41405390, 2026). "CPSF6-KO cells exhibited high SFLN5 levels, up to 20-fold the levels observed in wild-type or NT#H1 control cells, similar to the upregulation observed during HIV-1 infection." (PMID 41405390, 2026). "Using two independent methodologies to assess APA in human cell lines and primary CD4+ T cells, we found that HIV-1 infection regulates APA, shaped by the interaction of CPSF6 with the viral capsid, recapitulating the APA phenotype observed in CPSF6 knockout cells." (PMID 41405390, 2026). "Because we found that CPSF6-KO cells exhibit a consistent decrease in CPSF5 protein expression compared with wild-type cells, we tested whether HIV-1 infection decreases CPSF5 expression." (PMID 41405390, 2026). "To investigate the role played by HIV-1 infection–induced CPSF5 and CPSF6 translocation in infection-induced changes in APA, we infected A549 cells with HIV-1 bearing the capsid mutation N74D (HIV-1-N74D) or A77V (HIV-1-A77V), which fail to induce CPSF5 and CPSF6 translocation to nuclear speckles." (PMID 41405390, 2026). "Because CPSF5 and CPSF6 control APA, we tested the hypothesis that HIV-1 infection modulates the APA functions of CPSF5 and CPSF6." (PMID 41405390, 2026). "Finally, HIV-1 infection was significantly reduced in cells expressing the CPSF6 chimeras with NP and MX2 NLSs, despite these NLSs conferring effective CPSF6-358 nuclear localization." (PMID 39823525, 2025). "Taken together, these data suggest that CPSF6 knock-out cells have a reduced responsiveness to IFN, which may in part explain the enhanced permissivity of CPSF6 knock-out cells to HIV-1 infection." (PMID 41385587, 2025). "This could explain why we observed fewer changes in 3’ UTR lengths following wild-type HIV-1 infection in primary CD4 + T cells as compared to HT1080 cells and may point to potential cell-type differences in CPSF6 function." (PMID 41385587, 2025). "Previous studies of HIV-1 infection in CPSF6 knock-out or knock-down cells primarily relied on immortalized cell line models that do not fully recapitulate key features of HIV-1 infection." (PMID 41385587, 2025). "Similarly, depletion of CPSF6 in primary, resting CD4+ T cells reduced HIV-1 infection in single-round infection assays." (PMID 40202316, 2025). "Our studies do not fully address the time scale at which CPSF6-mediated transcriptional reprogramming occurs following HIV-1 infection." (PMID 41385587, 2025). "In line with previous experiments that utilized MX2 as a model system, some NLSs failed to complement the nuclear localization defect of CPSF6-358, and as a result these chimeric proteins restricted HIV-1 infection in the cytoplasm." (PMID 39823525, 2025).
HIV-1 infection (continued). "In line with previous experiments, some NLSs failed to complement the nuclear localization defect of CPSF6–358, and as a result restricted HIV-1 infection in the cytoplasm." (PMID 38979149, 2024). "Therefore, HIV-1 infection relocalises CPSF6 to SC35-containing nuclear speckles, but in T-cells, CPSF6 already accumulates to some extent at these sites in the absence of infection." (PMID 38793552, 2024). "The known functions of CPSF6 in nuclear import and integration site selection are not sufficient to explain the enhanced permissivity to HIV-1 infection observed upon CPSF6 knock-out in primary CD4 + T cells." (PMID 39678349, 2024). "We next examined whether changes in CPSF6 localization led to disruption of CPSF6 function and changes in APA in a cell line model of HIV-1 infection." (PMID 39678349, 2024). "Finally, HIV-1 infection was significantly reduced in cells expressing the CSPF6 chimeras with NP and MX2 NLSs, despite these NLSs conferring effective CPSF6–358 nuclear localization." (PMID 38979149, 2024). "Remarkably, the hypertonic medium dramatically inhibited wild-type HIV-1 infection, but poorly affected viruses bearing the capsid changes N74D and A77V, which are viruses that do not induce the formation of CPSF6 condensates." (PMID 37414787, 2023). "Host proteins CPSF6, NUP153, and SEC24C are vital for HIV-1 infection." (PMID 36202818, 2022). "Cellular proteins CPSF6, NUP153 and SEC24C play crucial roles in HIV-1 infection." (PMID 36202818, 2022). "As such, we targeted the expression of five genes with roles in HIV-1 infection (CD4, CXCR4, PSGL-1, TRIM5α and CPSF6) as well as CD46, in part using gRNAs pre-tested for each target for the efficiency of editing and protein loss was assessed in part by confocal microscopy." (PMID 34949807, 2022). "CPSF6 puncta were also observed in the nuclei of cells at later time points after WT HIV-1 infection (data not shown)." (PMID 33758083, 2021). "Previous failure to detect CA on nuclear complexes in T cells has been due to epitope masking by the cellular CPSF6 protein and the current results thus indicate a common pathway for early HIV-1 replication in different cell types including primary target cells of HIV-1 infection." (PMID 33904396, 2021). "Depletion of CPSF6 in cells did not affect HIV-1 infection in HeLa cells or PBMC, as previously demonstrated, nor did it alter HIV-1 trafficking to the nucleus in HeLa cells." (PMID 33758083, 2021). "We also posit that the role of CPSF6 in transcription is independent of its previously known roles in alternative polyadenylation and preintegration complex targeting in HIV-1 infection." (PMID 34154414, 2021). "Unexpectedly, overexpressed CPSF6 did not affect HIV-1 infection in HeLa-Ctrl cells, but when we overexpressed CPSF6 in HeLa-MxB cells, 2-LTR circles and integrated DNA was reduced, although viral replication was not affected." (PMID 32600399, 2020). "Stratification of cells into quartiles according to CPSF6 staining intensity revealed a correlation between HIV-1 infection and CPSF6 staining intensity for wild-type HIV-1, but not for the A77V variant." (PMID 30672737, 2019). "RTC/PIC accumulation at the nuclear envelope was also observed for WT HIV-1 infection with normal CPSF6 levels at early, but not at late time points p.i., indicating that transfer across the nuclear envelope is a rate-limiting step as recently suggested." (PMID 30672737, 2019). "CPSF6 directly interacts with the viral CA via the same binding pocket as NUP153, and when re-localized to the cytoplasm, inhibits HIV-1 infection." (PMID 30084827, 2018). "Engagement of CPSF6 is not required for HIV-1 infection in transformed cell lines but is tightly correlated with dependence on the nuclear entry cofactors TNPO3, NUP153 and NUP358." (PMID 25356722, 2014).
HIV-1 infection (continued). "At present, one of the most confusing observations is the fact that, as for CypA, depletion or over expression of CPSF6 does not impact HIV-1 infection or replication in cell lines [3••,28,43••]." (PMID 24525292, 2014). "Full-length CPSF6 localizes to the nucleus and when overexpressed does not able to restrict HIV-1 infection." (PMID 23414560, 2013). "Because overexpression of a CPSF6 fragment, CPSF6-358, potently blocks HIV-1 infection, we tested whether overexpression of a full-length CPSF6 protein inhibits HIV-1 infection." (PMID 23622145, 2013). "While exogenously introduced full-length CPSF6 is predominantly nuclear and does not adversely affect HIV-1 infection, mislocalizing it to the cytoplasm by appending a nuclear export sequence inhibits infection." (PMID 24103892, 2013). "When CPSF6-358 was targeted to the nucleus by fusion to the SV40 NLS, HIV-1 transduction was no longer inhibited, indicating that CPSF6-358 needs to be in the cytoplasm to inhibit HIV-1 infection." (PMID 23414560, 2013). "To understand whether the cytosolic fraction of CPSF6 is responsible for the inhibition of HIV-1 in TNPO3-depleted cells, we tested the ability of a cytosolic full-length CPSF6 to block HIV-1 infection." (PMID 23622145, 2013). "Because both CPSF5 and CPSF6 are involved in the regulation of APA, a key cellular mechanism that controls gene expression, we tested the hypothesis that HIV-1 infection alters the nuclear localization of CPSF5 and CPSF6, thereby dysregulating APA and ultimately modifying cellular gene expression." (PMID 41405390, 2026). "However, infection with HIV-1 bearing the capsid mutants N74D and A77V did not induce APA changes, suggesting that HIV-1 infection–induced APA changes require the direct interaction of the capsid protein with CPSF6." (PMID 41405390, 2026). "In CPSF6-KO cells, the presence of HIV-1 infection did not produce a significant increase in SLFN5 levels compared to uninfected CPSF6-KO cells, indicating that in CPSF6-KO cells, the expression level of SLFN5, and consequently also the APA, reached its threshold." (PMID 41405390, 2026). "Although most established cell lines do not experience an overall drop in HIV-1 infection due to decreased CPSF6 expression or capsid binding to CPSF6, viral DNA integration is misdirected outside of gene-dense, transcriptionally active, host chromatin-to-heterochromatic, lamina-associated areas." (PMID 39859212, 2025). "In contrast, a recent study observed colocalization of CPSF6 with nuclear speckles in primary CD4+ T cells even in the absence of HIV-1 infection, indicating that CPSF6 may undergo less dramatic changes in localization following infection of this cell type." (PMID 41385587, 2025). "The results reported here are fully consistent with this notion, as we found that only full-length CPSF6, which contains an intact RSLD, formed CPSF6 condensates following HIV-1 infection, while the CPSF6-358 constructs lacking an RSLD remained pan-nuclear in distribution." (PMID 39823525, 2025). "Additionally, we tested two PY-NLSs, HNRNP A1 and UL79, and found that HNRNP A1 conferred CPSF6-358 nuclear localization and supported HIV-1 infection similarly as CPSF6-FL, while UL79 failed to rescue both CPSF6-358 nuclear localization and HIV-1 infection." (PMID 39823525, 2025). "Nuclear localization of CPSF6–358 does not uniformly rescue HIV-1 infection." (PMID 38979149, 2024). "Additionally, we tested two PY-NLS’s, UL79 and HNRNP A1, and found that HNRNP A1 conferred CPSF6–358 nuclear localization and supported HIV-1 infection similarly as CPSF6-FL, while UL79 failed to rescue both CPSF6–358 nuclear localization and HIV-1 infection." (PMID 38979149, 2024). "Our experiments revealed that CPSF5, but not CPSF7, co-localized with CPSF6 upon HIV-1 infection." (PMID 37414787, 2023). "In Nup35-knockdown cells, WT HIV-1 infection no longer leads to CPSF6 precipitation in the nucleus." (PMID 37355754, 2023).
HIV-1 infection (continued). "N74D HIV-1 infection was significantly reduced during CsA treatment, with or without CPSF6 KD." (PMID 33758083, 2021). "Taken together, it is clear that CPSF6 has an important, CA dependent function in early HIV-1 infection of macrophages, which may not be fully recapitulated in HeLa- or 293T-based reporter cell lines." (PMID 30672737, 2019). "Interestingly, the capsid mutation N74D was isolated by serial passage of HIV-1 viruses in human T-cells expressing a fragment derived from the cleavage and polyadenylation specificity factor subunit 6 (CPSF6) protein, which blocks HIV-1 infection before nuclear import." (PMID 23622145, 2013). "Curiously, siRNA depletion of CPSF6 does not affect HIV-1 infection." (PMID 24103892, 2013). "Because CPSF5 or CPSF6 depletion is known to induce the use of proximal polyadenylation signals (12, 38, 39, 43, –, 45), we tested the hypothesis that the relocalization of CPSF5 and CPSF6 to nuclear speckles during HIV-1 infection correlates with their functions and leads to APA dysregulation." (PMID 41405390, 2026). "Therefore, knocking out CPSF6 expression may not be the best approach to understand its contribution to wild type HIV-1 infection." (PMID 37414787, 2023). "Interestingly, depletion of CPSF6 alone did not affect HIV-1 infection." (PMID 23622145, 2013). "The functional consequences of HIV-1 infection–induced CPSF5 and CPSF6 translocation to nuclear speckles are not understood." (PMID 41405390, 2026). "Unlike in wild-type cells, HIV-1 infection did not induce CPSF5 translocation to nuclear speckles in CPSF6-KO cells, suggesting that CPSF5 translocation to nuclear speckles is dependent on CPSF6 translocation." (PMID 41405390, 2026). "Compared with wild-type HIV-1 infections, infections with HIV-1-N74D or HIV-1-A77V, which do not induce CPSF5 and CPSF6 translocation to nuclear speckles, resulted in a similar number of 3’UTR lengthening events but a reduced number of 3'UTR shortening events." (PMID 41405390, 2026). "For example, cleavage and polyadenylation specificity factor 6 (CPSF6) facilitates HIV-1 nuclear localization and infection, but an NLS mutant of CPSF6 does not promote HIV-1 infection." (PMID 40459262, 2025). "Our results would support this notion, as we found that only full-length CPSF6, which contains an intact RSLD, formed CPSF6 condensates following HIV-1 infection, while the CPSF6–358 constructs lacking an RSLD remained pan-nuclear in distribution." (PMID 38979149, 2024). "To test the specificity of HIV-1 infection–induced decreases in CPSF5 protein expression, we measured CPSF5 levels upon infection with HIV-1-A77V, which does not induce the translocation of CPSF5 and CPSF6 to nuclear speckles." (PMID 41405390, 2026).
hepatocellular carcinoma (11 papers, 2021 to 2025). A malignant tumor that arises from hepatocytes. "In cancers, CPSF6 plays an oncogenic role in hepatocellular carcinoma and gastric cancer by promoting the proliferation, migration, and invasion of cancer cells in vitro and in vivo via APA regulation." (PMID 40629911, 2025). "In this study, we explored the oncogenic mechanism of cleavage and polyadenylation-specific factor 6 (CPSF6) in hepatocellular carcinoma (HCC)." (PMID 38993554, 2024). "CPSF6 has been found to play an important role in tumorigenesis and progression such as gastric cancer and hepatocellular carcinoma." (PMID 36446361, 2022). "In this study, we investigated the role of cleavage factor I (CFIm) subunit CPSF6 in human hepatocellular carcinoma (HCC)." (PMID 33648552, 2021). "Different studies have reported that the high expression of CPSF6 may be a novel diagnostic and prognostic marker for several tumours, such as hepatocellular carcinoma (HCC), esophageal squamous cell carcinoma (ESCC), lung adenocarcinoma (LUAD) and breast cancer." (PMID 38416782, 2024). "The qRT-PCR results showed that TOMM40L, SNRPA, ILF3, CPSF6, and NUP205 were remarkably highly expressed in hepatocellular carcinoma." (PMID 37745063, 2023). "The mRNA expression of CPSF6 was obviously upregulated in hepatocellular carcinoma cells compared with THLE-3 cells and the mRNA expression of CPSF6 in Huh-7 cells was the highest." (PMID 34217312, 2021).